CCL2 (C-C motif chemokine ligand 2)
Diseases named in the same sentence as CCL2 in open-access papers (continued):
Sharing a sentence is not in itself a finding about the gene and the disease.
Obesity (continued). "In contrast, the deletion of CCL2 or its receptor (CCR2) in mice is followed by a significant reduction in the development of atherosclerotic plaques and obesity." (PMID 39275140, 2024). "Elevated MCP-1/CCL2 was reported in obese adults and obese Mexican American children, and the mechanism included obesity-inducing inflammatory and triggering NF-kB signaling." (PMID 38541912, 2024). "CCL2 mRNA levels are increased in the WAT of genetic and high-fat diet-induced obesity and genetic diabetes in mice." (PMID 39457105, 2024). "In obesity, increased production of proinflammatory cytokines, free fatty acids, monocyte chemoattractant protein 1 (MCP-1) and CCL2 leads to macrophage polarization in adipose tissue to the proinflammatory M1 phenotype." (PMID 39867890, 2024). "We validated our findings in vivo, demonstrating that individuals living with obesity show an inverse relationship between CKB expression and promoter methylation in white adipocytes, along with elevated CCL2 secretion." (PMID 39675471, 2024). "In accordance with inflammatory cell infiltration, an upregulation (P<0.05) in transcript levels of chemokine MCP-1 (Ccl2) and cytokine TNF-α (Tnf) was observed in the pancreas of rats with diet-induced obesity." (PMID 37274331, 2023). "They employed a high-fat diet-induced murine model of obesity and discovered a significant increase in TNF-α and Ccl2 mRNA levels in obese mice, which were tightly correlated with the histone H3 acetylation augmentation." (PMID 37862340, 2023). "IL-6, IL-8, IL-15, TNF-α, MCP-1 (CCL2) and other molecules, such as fibroblast growth factor 21, irisin, myonectin, and myostatin, are involved in obesity with insulin resistance or type 2 DM." (PMID 36552805, 2022). "Obesity phenocopies aging with increased BMA, which has been shown to induce CCL2/MCP-1 and COX-2 within the BM, emphasizing a close relationship between immune response and BMA." (PMID 35360075, 2022). "CCL2 and CCL5 have been reported to increase, particularly in the ATM fraction, with obesity, and are correlated with T cells in adipose tissue." (PMID 35052852, 2022). "Previous reports indicated that MAPK1 contributes to the elevated secretion of monocyte chemoattractant protein-1 (MCP-1), and MAPK3 is associated with enhanced mRNA levels of inflammatory markers, such as CCL2, IL1β, and TNF-α in obesity." (PMID 34360840, 2021). "In humans, PVAT samples from obese subjects showed that the expression of MCP1/CCL2, CCL8, IL1beta, and IL6 proteins were upregulated, suggesting that obesity triggers upregulation of pro-inflammatory factors secreted by PVAT." (PMID 34948944, 2021). "As results, the identified findings using network pharmacology analysis had identified total six hug genes of metformin treating obesity/hypertension, including IL6, CCL2, LEP, APOB, SERPINE1, and APOE." (PMID 34334083, 2021). "Using this algorithm, all hug targets of metformin against obesity-related hypertension were identified accordingly, including IL6, CCL2, Leptin (LEP), Apolipoprotein B (APOB), serine protease inhibitor clade E member 1 (SERPINE1), Apolipoprotein E (APOE)." (PMID 34334083, 2021). "In obesity, the secretion of multiple cytokines including IL-3, IL-7, IL-8, TNFα and chemokines including monocyte chemotactic protein-1 (MCP-1, also called Chemokine C-C motif ligand 2 (CCL2)), are upregulated." (PMID 33105727, 2020). "Weight loss and therapies targeting HC, TNF-α and CCL2, whether separately or in combination, may be beneficial to modulate rates of CSF secretion and/or resistance to CSF drainage pathways, both factors likely contributing to the raised ICP observed in female IIH patients with obesity." (PMID 32036786, 2020). "Obesity induces insulin, IGFs, leptin, IL-6, TNF-α, CCL2, and PAI-1, reduces adiponectin, and disturbs gut microbiota and bile acid homeostasis." (PMID 32486076, 2020).
Obesity (continued). "Adipocytes are capable of secreting pro-inflammatory cytokines, including CCL2, TNF-α, and IL-6 and their production is significantly increased in obesity." (PMID 32318345, 2020). "CCL2, CCL8 and interleukin-6 are well-studied pro-inflammatory cytokines that are chronically elevated in obesity but they have also be identified as contraction-regulated myokines that have beneficial effects after exercise when levels increase acutely." (PMID 32232327, 2020). "During obesity, circulating Ly6C+ CCR2high bone marrow-derived monocytes are recruited to the adipose tissue through a CCL2 (MCP-1)/CCR2-mediated mechanism." (PMID 32709161, 2020). "Adipose tissue of individuals with obesity exhibit elevated expression of TNF-α, IL-6, CCL2, FFAs, and IL-8 when compared with normo-weight controls." (PMID 31443599, 2019). "Taken together, our results suggest that obesity promotes CNS inflammation in EAE through IL-6 and CCL-2 mediated the inflammatory cells infiltration." (PMID 31507583, 2019). "Several studies have demonstrated consistently higher levels of IL-8, FFAs and TNF-α in the circulation of individuals with obesity/T2D and we recently showed that coexistent of TNF-α and saturated fatty acids enhanced CCL2 production." (PMID 31443599, 2019). "Inflammatory cytokines including C-C chemokine ligand 2 (CCL2), TNF-α, and interleukin-6 are increased in obesity." (PMID 31498850, 2019). "Our study suggested that obesity promotes CNS inflammation in EAE through enhanced autoreactive T cell immune responses mediated by IL-6 and CCL-2." (PMID 31507583, 2019). "The C–C motif chemokine ligand 2/monocyte chemoattractant protein 1 (CCL2/MCP-1) has been documented to regulate metabolism, inflammatory responses, obesity, and insulin resistance amongst others." (PMID 29922517, 2018). "With the development of obesity, adipocytes can release proinflammatory mediators, such as CC chemokine ligand (CCL)-2 (also known as MCP-1), tumor necrosis factor (TNF)-α, free fatty acids (FFAs), which recruit M1 macrophage." (PMID 29415997, 2018). "It was proposed by Frasca and Blomberg that increased hypoxia and CCL-2 expression, along with increased adipocyte-derived TNF-α, IFN-γ, IL-6, and IL-21, prompted an obesity-driven accumulation of pro-inflammatory B-cells, which is exacerbated with ageing." (PMID 29479350, 2018). "In the adipose tissue, increased CCL2 signaling through its receptor, CCR2, links obesity and insulin resistance through the induction of an inflammatory response." (PMID 27832159, 2016). "Certain functions of CCR2 have been revealed when it binds CCL2 forming CCL2/CCR2 axis, involving formation of atherosclerotic plaques, insulin resistance in obesity, and inflammatory responses against tumors." (PMID 26701209, 2016). "This is consistent with our analyses of GAL in the PVN, a neuropeptide that is positively related to a HFD and increased in a state of dietary obesity and, while unaffected by CXCL12 as shown here, is stimulated by another chemokine, CCL2." (PMID 27047354, 2016). "Monocyte chemoattractant protein (MCP)-1, also known as C-C chemokine ligand (CCL)-2, recruits monocytes to the sites of inflammation, such as into the expanding adipose tissue in obesity/T2D or the arterial vessel wall in asthmatic patients." (PMID 27709105, 2015). "Several studies have shown an important role of adipose tissue macrophages in inflammation in obesity through the production and release of proinflammatory mediators such as IL-1, TNF-α, IL-6, and CCL2." (PMID 24398136, 2014). "Macrophage infiltration has been by far the most investigated in obesity, and several groups have studied the role of chemokines (chemoattractant cytokines) such as CCL2/MCP-1 (C-C motif chemokine ligand 2/macrophage chemoattractant protein-1)." (PMID 23824685, 2013). "Monocyte chemoattractant protein-1 (MCP-1, CCL2) is involved in insulin resistance of obesity and type 2 diabetes." (PMID 21589925, 2011).
Obesity (continued). "Main topics cover the relationship between MCP-1/CCL2, insulin resistance, inflammation, obesity, and related metabolic disturbances." (PMID 20936118, 2010). "In contrast, IL-1β and CCL2 reflect obesity-related inflammatory burden rather than early metabolic changes, while IL-6 and IL-15 did not reflect early metabolic alterations in this study." (PMID 42196825, 2026). "The expression and secretion of many adipokines, such as leptin, resistin, tumor necrosis factor-α (TNF-α), interleukin-6 (IL-6), C-C motif chemokine ligand 2 (CCL2), CXC motif chemokine ligand 5 (CXCL5), and angiopoietin-like 2, are up-regulated in AT during obesity." (PMID 40076419, 2025). "Moreover, C‐C motif chemokine 2 (CCL2) and KDM6A expression was higher in the group with obesity, as were CREBBP and EP300." (PMID 40518865, 2025). "Obesity is a systemic chronic metabolic inflammation, with upregulation of inflammatory markers such as tumor necrosis factor (TNF-α), interleukins (IL)-6, IL-1β, and CCL2 in the adipose tissue of obese individuals." (PMID 39050542, 2024). "Typically, in mouse models of obesity, many studies have shown increased CCL2 levels in adipocytes and/or plasma, but no data on the role of CCL2 in obesity-induced hypersensitivity have been reported." (PMID 39457105, 2024). "With this background, we intend to study the relationship between pro-inflammatory chemokines CCL1, CCL2, CCL4, and CCL5 and the etiopathogenesis of T2DM in subjects with varying levels of obesity, BMI, and HbA1c in a patient cohort from the Asir region of Saudia Arabia." (PMID 39063997, 2024). "Individuals with obesity have higher volumes of pathological VAT, with increased infiltration by macrophages attracted by adipocyte-derived monocyte chemoattractant protein (MCP-1/CCL-2) and other inflammatory chemokines." (PMID 37233716, 2023). "Obesity was shown to increase the expression of many proinflammatory markers, including CRP, plasminogen activator-1 inhibitor, IL-6 and TNFα, monocyte chemokine CCL2, or MCP-1, and acute phase protein—serum amyloid." (PMID 36138973, 2022). "As is known, CCL2, also known as monocyte chemoattractant protein-1 (MCP-1), is primarily produced in the stromovascular fraction of PPAT, and its expression increases in obesity and correlates with decreased survival in patients with PCa." (PMID 35406450, 2022). "For instance, nitration of tyrosine residues in CCL2 by reactive nitrogen species reduces the ability of this chemokine to attract monocytes through its receptor CCR2, which might be involved in obesity-induced adipose tissue inflammation." (PMID 34948325, 2021). "In a comparison of age-, sex-, and BMI-matched patients with metabolically healthy obesity either with preserved insulin sensitivity or insulin resistance, we found that neither CCL2 serum concentrations nor AT expression are related to AT inflammation." (PMID 33540898, 2021). "Expansion of subcutaneous and visceral adipose tissue compartments in obesity leads to hypoxia-induced hypersecretion of adipocytokines such as tumour necrosis factor (TNF)α, interleukin (IL)-6 and monocyte chemoattractant protein-1 (MCP-1/CCL2) by adipocytes." (PMID 34113839, 2021). "In addition, further studies on the associations between CCL2 on inflammation of the arachnoid villi, hyperandrogenism and PCOS, may highlight a possible role in the cause of increased resistance to CSF drainage and elevated ICP in female IIH patients with obesity." (PMID 32036786, 2020). "Besides, because of obesity, the HFDM1 group demonstrated low-grade inflammation in visceral adipose tissue through enhancing production of inflammation-related cytokines, Ccl2 and Tnf-α." (PMID 32733406, 2020).
Obesity (continued). "In some circumstances, such as hepatic inflammation typical of severe obesity, peripheral circulating inflammatory cytokines like TNFα are required to stimulate microglia to produce MCP-1/CCL2 and cerebral monocytes and to activate vagal afferent neurons to induce central inflammation." (PMID 32106469, 2020). "Obesity, as a characteristic of metabolic syndrome, is related to chronic low-grade inflammation in obese subjects, because of various pro- and anti-inflammatory cytokines produced by adipose tissues, including IL-6, TNF-α, CCL2, PAI-1, and others." (PMID 32486076, 2020). "Moreover, investigators showed that blocking CCL2/CCR2 signaling pathway can ameliorate renal injury and proteinuria in a mouse model of obesity and insulin resistance." (PMID 31919470, 2020). "In obesity, excess M1 type macrophages not only accumulate in adipose tissue but also in liver, where they produce the chemokine (C-C motif) ligand 2/monocyte chemotactic protein-1 (CCL2/MCP-1)." (PMID 31800592, 2019). "We extended this exploration to pre-adipocytes, CD31+ endothelial cells and mature adipocytes, focusing on a set of inflammation-related genes (CCL2, CCL20, IL-8, IL-6 and pro-IL-1β) selected among genes known to be up-regulated in adipose tissue with human obesity." (PMID 28592801, 2017). "Also, in the obesity, inflammation can result due to increased inflammatory cytokines (TNF-α, IL6, IL1β, etc.)and chemokines (CXCL1, CCL2, etc.)secreted from adipocytes and accumulated fat in the liver inducing insulin resistance." (PMID 28598982, 2017). "Strategies to suppress the CCL2/CCR2 signal may only partially inhibit ATM accumulation and insulin resistance at the late stage of obesity." (PMID 27031964, 2016). "However, at a later stage of obesity (HFD for >12 weeks), a significant higher level of CCL2 in the serum was found." (PMID 27031964, 2016). "We found that macrophage numbers were decreased 78.3% in CD1df/f-adipoq-cre mice compared with control mice, likely due to reduction of CCL2 in these animals, suggesting that adipocyte-NKT cell interactions are critical for recruitment of macrophages in adipose tissue during obesity." (PMID 27329323, 2016). "It is conceivable that local and systemic expression of NOV could be related to TNF-α expression because this cytokine is locally increased in obesity and mediates the induction of obesity-related factors such as TGF-β, PAI-1 and CCL-2." (PMID 23785511, 2013). "Chemokine (C-C motif) Ligand 2 (CCL2) is produced by immune and metabolic cells and attracts immune cells into liver, muscle and adipose tissue, resulting in initiation and propagation of the inflammatory response in obesity." (PMID 23557387, 2013). "First, an intact CCL2/CCR2 axis, the principal chemotactic pathway, is necessary for understanding the mechanistic links between adipose tissue inflammation and the effects of obesity." (PMID 20936118, 2010). "In conclusion, our findings suggest that leptin, through its effects on H3K27 epigenetic changes, plays a pivotal role in regulating CCL2/MCP‐1 expression in ASCs, revealing a novel mechanism by which leptin may contribute to WAT inflammation and the pathophysiology of obesity." (PMID 40518865, 2025). "In detail, it is proved that in obesity, chronic low-grade inflammation is present since adipose tissue produces pro-inflammatory cytokines (e.g., TNF-α, IL-6), chemokines (monocyte chemoattractant protein (MCP1/CCL2), and pro-inflammatory fatty acids, leading to systemic inflammation." (PMID 40566087, 2025). "The relationship between obesity and insulin resistance is driven by adipose tissue inflammation, which stimulates cytokine and chemokine release [including interleukin 6 (IL-6), tumor necrosis factor-alpha (TNF-α), and chemokine (C-C motif) ligand 2 (CCL2)] and macrophage recruitment." (PMID 39928502, 2025).
Obesity (continued). "However, the mRNA levels of individual Tnfa, Il1b, or Ccl2 are differentially expressed among CD9+CD11c-, CD9-CD11c+, and CD9+CD11c+ ATMs, suggesting functional heterogeneity even among proinflammatory ATMs during obesity." (PMID 40244655, 2025). "In addition to CCL2/CCR2, other chemokines and their receptors may play a role in the increased macrophage accumulation in adipose tissue in obesity." (PMID 37153549, 2023). "With the occurrence of obesity, the immune cells in adipose tissue infiltrate and produce inflammatory factors, such as tumor necrosis factor-α (TNF-α), interleukin (IL), and C-C motif chemokine ligand 2 (CCL2), promoting local or systemic inflammatory responses." (PMID 37853356, 2023). "Interestingly, these findings are consistent with evidence demonstrating that the exercise-induced reshaping of WAT functionality warrants a decrease in CCL-2, suggesting that the modulation of WAT may be critical for regulating plasma CCL-2 levels in obesity." (PMID 36829858, 2023). "MCP-1, also known as CCL2, plays a central role in the pathogenesis of several different disease processes, including vascular permeability and attraction of immune cells during metastasis, various neurological disorders, autoimmune disease, obesity, and atherosclerosis." (PMID 37629196, 2023). "Finally, CCL2 is not required in some infection models, nor is CCL2 required for macrophages to invade and clear thrombi, or invade adipose tissue in obesity." (PMID 35820932, 2022). "Additionally, levels of CCL2 and CRP decreased with gestational age in mothers with obesity." (PMID 34195568, 2021). "Among cytokines, chemokine (C-C motif) ligand 2 (CCL2), also named monocyte chemoattractant protein 1 (MCP1), is produced by tumor cells and by various other cells in the host microenvironment, including adipocytes, and was reported upregulated in various tumors, including CRC, and in obesity." (PMID 34639088, 2021). "In obese mice and subcutaneous adipose tissue from obese women, CCL2 was increased in breast adipose tissue and enhanced the glucocorticoid-mediated CYP19A1 transcription, thus promoting the pro-inflammatory milieu and aromatase expression under obesity condition." (PMID 34350120, 2021). "However, CCL2 deficiency does not affect macrophage infiltration or insulin sensitivity, suggesting that CCL2-CCR2 signaling is not critical for obesity-induced macrophage recruitment or systemic insulin resistance." (PMID 34360773, 2021). "Thus, adipose IRF5 transcripts in obesity correlate positively with TNF-α, IL-1β, IL-6, CXCL8/IL-8, CXCL9/MIG, CXCL10/IP10, CCL2/MCP1, CCL5, and CCL7/MCP3, all of which can be elevated in COVID-19 “cytokine storm”; positive correlations with IL-2 and IL-12 have been reported by the same group." (PMID 33936053, 2021). "Many reports link obesity with increased CCL2 production, although none discuss kidney recipients." (PMID 34768469, 2021). "However, we also noted discordance between gene and protein expression of CCL2 and CCL5 in the adipose tissue which may be due to variability in the stabilities of their mRNAs and proteins in the adipose tissue in obesity." (PMID 31718015, 2019). "In particular, pro-inflammatory macrophage accumulation in adipose tissue is an important feature of obesity, correlating with local expression of inflammatory markers including tumor necrosis factor-α (TNF-α), interleukin-6 (IL-6), interleukin-1β (IL-1β) and C-C Motif Chemokine Ligand 2 (CCL2)." (PMID 31443599, 2019). "Consistently, the level of CCL2 in serum was not changed at the early stage of obesity." (PMID 27031964, 2016). "Besides CCL2/MCP-1, several other chemokines such as CCL5, C-X-C motif chemokine ligand 5 (CXCL5) and CXCL14 are also involved in adipose tissue macrophage infiltration and obesity-induced insulin resistance." (PMID 24733068, 2014).